RNU7-195P (RNA, U7 small nuclear 195 pseudogene)
Gene: Small nuclear RNA gene on chromosome 15 (89,120,779 to 89,120,840, forward strand). Ensembl gene ENSG00000239151.
Homologues: Orthologues: chimpanzee U7 (98% identical), macaque U7 (77% identical). Paralogues in human: RNU7-35P (79% identical), RNU7-7P (79% identical), RNU7-121P (77% identical), RNU7-124P (77% identical), RNU7-130P (77% identical), RNU7-141P (77% identical), RNU7-152P (77% identical), RNU7-20P (77% identical), RNU7-37P (77% identical), RNU7-53P (77% identical), RNU7-62P (77% identical), RNU7-73P (77% identical), and 143 more.